XIST (X inactive specific transcript)
Diseases named in the same sentence as XIST in open-access papers (continued):
Sharing a sentence is not in itself a finding about the gene and the disease.
gastric cancer (continued). "More recently, upregulation of XIST was reported to be associated with overexpression of EZH2, a key component of PRC2 and to act as an adverse prognosis indicator of gastric cancer patients." (PMID 29100288, 2017). "Recent studies have indicated that XIST was aberrantly expressed in several cancers, including gastric cancer, lung cancer, pancreatic cancer, hepatocellular carcinoma and osteosarcoma." (PMID 29212233, 2017). "The results showed that lncRNA XIST expression was significantly increased in gastric cancer tissues as compared with adjacent normal tissues (P < 0.001)." (PMID 27620004, 2016). "In this study, we demonstrated that lncRNA XIST was significantly overexpressed in gastric cancer tissues and cell lines." (PMID 27620004, 2016). "Real-time PCR was performed to confirm the successful knockdown of lncRNA XIST in gastric cancer cells (*P < 0.05)." (PMID 27620004, 2016). "In our study, we found the expression level of lncRNA XIST was significantly higher in gastric cancer tissues than that of adjacnet normal tissues." (PMID 27620004, 2016). "Overexpression of lncRNA XIST was markedly associated with larger tumor size, lymph node invasion, distant metastasis and TNM stage in gastric cancer patients." (PMID 27620004, 2016). "The biological function of lncRNA XIST on gastric cancer cells were determined both in vitro and in vivo." (PMID 27620004, 2016). "lncRNA XIST level was significantly higher in gastric cancer cell lines (SGC7901, HGC27, BGC823, MKN45, MKN28, AGS) than that of normal gastric epithelial cell GES-1 (*P < 0.05, **P < 0.001)." (PMID 27620004, 2016). "In this study, we found that lncRNA XIST expression was significantly up-regulated in gastric cancer tissues and cell lines and affected clinicopathological characteristics and prognosis in gastric cancer patients." (PMID 27620004, 2016). "Due to the long sequence of lncRNA XIST, we knockdown the expression of lncRNA XIST in gastric cancer cells." (PMID 27620004, 2016). "The regulating relationship between lncRNA XIST and miR-101 was investigated in gastric cancer cells." (PMID 27620004, 2016). "The significant increased expression of lncRNA XIST in gastric cancer tissues prompted us to investigate its biological role in gastric cancer cells." (PMID 27620004, 2016). "In gastric cancer, XIST has been shown to exert oncogenic effects." (PMID 34179019, 2021). "This study found that XIST acts as an oncogenic lncRNA in gastric cancer." (PMID 34946859, 2021). "Furthermore, miR-497 has been reported to be the target of XIST in gastric cancer and hepatocellular carcinoma." (PMID 33364236, 2020). "Therefore, our data here indicated that higher XIST expression in the tumor tissues of patients with gastric cancer, nasopharyngeal carcinoma, pancreatic cancer, osteosarcoma or esophageal squamous cell carcinoma were associated with a shorter OS." (PMID 29568404, 2018). "For instance, XIST is upregulated in gastric cancer and inhibits expression of EZH2." (PMID 29100288, 2017). "lncRNA XIST is up-regulated and is associated with aggressive tumor phenotypes and patient survival in gastric cancer, and the newly identified lncRNA XIST/miR-101/EZH2 axis could be a potential biomarkers or therapeutic targets for gastric cancer patients." (PMID 27620004, 2016). "Moreover, transwell and wound healing assays demonstrated that the cell invasion and migration was markedly suppressed in gastric cancer cells transfected with si-XIST as compared with cells transfected with si-NC (*P < 0.05)." (PMID 27620004, 2016). "In addition, the lncRNA XIST expression level was markedly correlated with the TNM stage of gastric cancer patients (*P < 0.05, **P < 0.001)." (PMID 27620004, 2016). "lncRNA XIST was significantly up-regulated in gastric cancer tissues and cell lines." (PMID 27620004, 2016).
gastric cancer (continued). "We first used the bio-informatic tools to search for the potential miRNAs that can be regulated by lncRNA XIST, to our interest, miR-101, which has been found to be down-regulated in gastric cancer, could bind to lncRNA XIST." (PMID 27620004, 2016). "Real-time PCR analysis was performed to measure the expression levels of lncRNA XIST in gastric cancer tissues and cell lines, the correlation between lncRNA XIST expression and clinicopathological characteristics and prognosis was analyzed in gastric cancer patients." (PMID 27620004, 2016). "lncRNA XIST level was then determined in gastric cancer cell lines by real-time PCR analysis." (PMID 27620004, 2016). "To determine whether lncRNA XIST is associated with gastric cancer development, we first measured the expression level of lncRNA XIST in gastric cancer tissues." (PMID 27620004, 2016). "At our research center, qPCR analysis revealed that XIST expression was significantly elevated in gastric cancer (GC) tissues compared to normal gastric mucosa tissues." (PMID 40860183, 2025). "Here, we unveil a previously unrecognized NAT10/XIST/YAP1/VEGFA signaling axis driving vascular abnormalization in gastric cancer (GC) and demonstrate its therapeutic potential in remodeling the tumor immune microenvironment." (PMID 40860183, 2025). "Based on these results, we concluded that XIST might serve as a prognostic biomarker in human cancers of gastric cancer, hepatocellular carcinoma, nasopharyngeal carcinoma, pancreatic cancer, osteosarcoma, esophageal squamous cell carcinoma and cervical squamous cell carcinoma." (PMID 29568404, 2018). "The results of the forest plot demonstrated that gastric cancer, pancreatic cancer, osteosarcoma, esophageal squamous cell carcinoma or cervical squamous cell carcinoma patients with higher expression of XIST in the tumor tissues may have increased probability of high tumor stages." (PMID 29568404, 2018). "Therefore, we provided the first evidence that knockdown of lncRNA XIST could inhibit gastric cancer progression and metastasis by modulating the miR-101/EZH2 pathway." (PMID 27620004, 2016). "Moreover, to evaluate whether the expression of lncRNA XIST was an independent prognostic factor for gastric cancer, univariate and multivariate analyses were performed." (PMID 27620004, 2016). "Besides, we did western blot to test whether XIST can affect epithelial-mesenchymal transition (EMT) in gastric cancer cells." (PMID 27620004, 2016). "In addition, knockdown of lncRNA XIST could suppress the colony formation and invasion ability stimulated by miR-101 in gastric cancer cells." (PMID 27620004, 2016). "However, the expression and biological function of lncRNA XIST in gastric cancer is unclear." (PMID 27620004, 2016). "Moreover, knockdown of lncRNA XIST could inhibit gastric cancer cell proliferation and invasion in vitro as well as tumorigenesis and metastasis in vivo." (PMID 27620004, 2016). "Our previous studies on the function of lncRNA XIST in gastrointestinal cancers showed that lncRNA XIST was a meaningful biomarker to predict prognosis in CRC and gastric cancer, which was also confirmed by DL." (PMID 33666372, 2021). "However, the role and molecular mechanism of lncRNA XIST in gastric cancer is still unknown." (PMID 27620004, 2016). "Taken together, targeting the NAT10/XIST/YAP1 axis-mediated vascular abnormalization by using Remodelin and Verteporfin could enhance immune checkpoint blockade in gastric cancer." (PMID 40860183, 2025). "For instance, lncRNAs CCAT1, XIST and LINC00152 were reported to promote cancer progression by functioning as miRNA sponges in hepatocellular carcinoma, gastric cancer and gallbladder cancer." (PMID 31781561, 2019).
gastric cancer (continued). "In summary, our study uncovered that NAT10-mediated ac4C modification stabilizes lncRNA XIST, which recruits hnRNPK to facilitate YAP1 nuclear translocation and transcriptional activation, thereby driving VEGFA-dependent vascular abnormalization in gastric cancer." (PMID 40860183, 2025). "Thus, we hypothesized that XIST recruits hnRNPK to promote the nuclear translocation of the YAP1 protein and YAP1/TEAD4-mediated VEGFA transcription in gastric cancer cells." (PMID 40860183, 2025). "LncRNA XIST expression is up-regulated in several cancers, however, its modulatory mechanism in gastric cancer (GC) has not been elucidated." (PMID 27911852, 2017).
lung cancer (37 papers, 2015 to 2026). A malignant neoplasm involving the lung. "In summary, the data implied that XIST had a vital role in lung cancer progression and functioned as a diagnostic and therapeutic target for lung cancer." (PMID 34930117, 2021). "In this study, we investigate changes in the transcriptional landscape of cell lines from male and female patients with NSCLC where XIST was downregulated and studied the expression and correlation of associated genes in lung cancer." (PMID 33255394, 2020). "Meanwhile, according to the study, the XIST/miR-374A/LARP1 axis is associated with lung cancer." (PMID 36353111, 2022). "Recently XIST has been implicated in the development of lung cancer." (PMID 33255394, 2020). "Finally, we showed that expression of XIST with another 4 genes provided a strong diagnostic potential to discriminate lung cancer from healthy controls." (PMID 33255394, 2020). "In particular, the lncRNA XIST has a remarkable function in the occurrence of several cancer types, including brain tumours, leukaemia, and liver, breast, bladder and lung cancers." (PMID 38317244, 2024). "In lung cancer, lncRNAs XIST and FAM83A-AS1 inhibit miR-141 leading to induction of EMT, increased growth, migration, invasion, and metastasis." (PMID 37511619, 2023). "In this study, the authors proved that the conditioned medium of lung cancer cells induced XIST and promoted the expression of M2-related genes in macrophages." (PMID 39698297, 2023). "A decrease in the expression level of XIST in lung cancer cells significantly reduced their proliferation and invasion." (PMID 36035993, 2022). "Expression levels of XIST have also been shown to be appropriate markers for follow-up of patients with lung cancer, since they have been reduced following surgical removal of tumors." (PMID 34179019, 2021). "XIST has also been shown to be over-expressed in lung cancer cell lines promoting their proliferation ability through sponging miR-140." (PMID 34179019, 2021). "XIST can modulate resistance to chemotherapeutic agents in a number of cancers including breast and lung cancers." (PMID 34179019, 2021). "Expression of XIST expression has also been up-regulated in cisplatin-resistant lung cancer cells compared with the original cells." (PMID 34179019, 2021). "At present, research on 1ncRNAs in cisplatin resistance in lung cancer was still in its infancy, and some lncRNA molecules related to cisplatin resistance in lung cancer had been screened and identified, including H19, XIST, SFTA1P, CCAT1, and MALAT1." (PMID 32626737, 2020). "Early studies indicated that XIST interacted with miR-140-5p to control lung cancer growth, as well as enhanced pancreatic carcinoma development." (PMID 30858762, 2019). "Of the 864 miRNA predicted to bind XIST by sequence homology, our results suggest that less than 2% of these show promise to be biologically-involved in lncRNA sponging of miRNAs in lung cancer." (PMID 31419261, 2019). "First, the EV-RNA signatures, low EV-miR-21-5p and high miR-486-3p, MEG3 and XIST identified in this study require clinical validation in a larger patient cohort to confirm their prognostic relevance in ALK-translocated lung cancer." (PMID 30658414, 2019). "In addition, many studies confirmed that XIST gene can participate in many cancer processes, such as breast cancer, ovarian cancer, and lung cancer." (PMID 35109760, 2022). "For example, XIST is aberrantly overexpressed in bladder, colorectal, and lung cancers." (PMID 35723009, 2022). "However, the oncogene lncRNA plasmacytoma variant translocation 1 (PVT1), XIST, and MALAT1 have all been demonstrated to promote autophagy through LC3 cleavage, which can enhance the chemoresistance of lung cancer cells." (PMID 33931980, 2021). "XIST also plays a crucial role in ovarian cancer, non–small cell lung cancer, and glioblastoma." (PMID 34354991, 2021).
lung cancer (continued). "Both lncRNA X‐inactive‐specific transcript (XIST) and bladder cancer‐associated transcript 1 (BLACAT1) can bind to miR‐17 and target autophagy‐related 7 (ATG7) to promote autophagy and reduce the chemosensitivity of lung cancer cells." (PMID 33931980, 2021). "XIST silencing has repressed proliferation and enhanced apoptosis of lung cancer cells." (PMID 34179019, 2021). "Our study provides a novel insight into the role of XIST in lung cancer." (PMID 33255394, 2020). "The rationale for targeting XIST in cancers is based on hypothesis and empirical data suggesting that modulating XIST expression and/or its miRNA-regulatory functions may inhibit the progression of bladder, colorectal and lung cancers." (PMID 41601966, 2026). "Finally, lncRNA XIST may be a useful biomarker regulating cisplatin resistance in lung cancer cells and further, we explored the BAX may effect tumor-infiltrating immune cells." (PMID 33390811, 2021). "Moreover, XIST was widely reported to promote lung cancer progression." (PMID 34243729, 2021). "XIST-mediated sequestration of RBM5 mRNA leads to decreased protein expression levels, resulting in enhanced proliferation and survival of lung cancer cells." (PMID 39201688, 2024). "A notable example is the lncRNA XIST, which interacts with the mRNA of the tumor suppressor gene RBM5 (RNA Binding Motif Protein 5) in lung cancer cells." (PMID 39201688, 2024). "In lung cancer, TCF-4 positively regulates lncRNA XIST expression in TAM by directly binding to the promoter region of XIST gene." (PMID 36263199, 2022). "The research suggested that lncRNA XIST can regulate the expression of TCF-4, and then regulate the polarization of macrophages in lung cancer." (PMID 35109760, 2022). "The upregulation of TCF-4/lncRNA XIST contributes to TAM phenotypic transformation and M2 polarization, which drive tumor progression in lung cancer." (PMID 36263199, 2022). "As XIST, its positive regulator JPX has an oncogenic role in lung cancer, at least partly due to ceRNA mechanisms." (PMID 35054794, 2022). "The results showed that lncRNA XIST positively regulated the M2 polarization and interacted with TCF-4, thus regulating the development of lung cancer." (PMID 35145526, 2022). "The top 5 long non-coding RNAs that use the IPCARF algorithm to predict lung cancer are: GAS5,XIST,CDKN2B-AS1, PVT1 and HOTAIR." (PMID 33794766, 2021). "The expression of XIST and co-regulated genes TSIX, hnRNPu, Bcl-2, and BRCA1 analyses in lung cancer (LC) and controls were performed in silico." (PMID 33255394, 2020). "Leveraging the available large-scale sequence data from TCGA and GTEX, we demonstrate that XIST, TSIX, hnRNPu, Bcl-2, and BRCA1 are differentially expressed in two different types of lung cancer when compared to controls." (PMID 33255394, 2020). "For example, in all earlier studies, XIST expression was not stratified in male and female lung cancer patients and numbers were considerably lower to the ones assessed in this study." (PMID 33255394, 2020). "However, lncRNA XIST knockout can restore IL-4-induced M2 polarization, further indicating the importance of TCF-4 in M2 Mφs and TAMs-induced proliferation, migration and invasion of lung cancer cells." (PMID 35145526, 2022). "Upregulated XIST, MALAT1, and NEAT1 lncRNAs were predicted to modulate and promote cell development and further metastasis in multiple cancers through mir-124-3p, but no studies in lung cancer were done regarding other functions of these lncRNAs, or their response to VRB." (PMID 38137519, 2023).
ovarian carcinoma (36 papers, 2011 to 2025). A malignant neoplasm originating from the surface ovarian epithelium. "The downregulation of XIST was associated with a higher stemness index and an unfavorable prognosis, suggesting that XIST plays a role in regulating ovarian cancer SCs." (PMID 39546568, 2024). "XIST KD also resulted in an enrichment of the epithelial-to-mesenchymal hallmark in ovarian cancer cells, consistent with observed morphological changes." (PMID 39546568, 2024). "We demonstrate that XIST loss unlocks cancer cell stemness and cellular plasticity in ovarian cancer." (PMID 39546568, 2024). "By analyzing the downregulation of XIST associated with poorly differentiated ovarian cancer grades and its correlation with poor overall survival, we identified the significance of XIST in determining cancer cell stemness and cellular characteristics." (PMID 39546568, 2024). "Our study using XIST knockdown (KD) in ovarian cancer cell lines demonstrated how XIST affects cancer SC heterogeneity and that the loss of XIST lncRNA promotes cancer cell invasion and migration." (PMID 39546568, 2024). "XIST can regulate the polarization of tumor-associated macrophages through miR-101-3p and then promote the proliferation and migration of breast and ovarian cancer cells." (PMID 36035993, 2022). "Downregulation of ADAMTS9‐AS2 or XIST is associated with progression of cell proliferation and malignant behaviors in ovarian cancer." (PMID 32684827, 2020). "The loss of inactive X chromosome has been suggested as a mechanism for the loss of XIST transcripts in the ovarian cancer cell lines." (PMID 27664137, 2017). "In the same study, a reduced expression of XIST in several ovarian cancer cell lines was associated with an increased resistance to paclitaxel." (PMID 26992233, 2016). "In ovarian cancer cell lines, XIST expression is decreased and associated with loss of X inactivation." (PMID 26992233, 2016). "In ovarian cancer, a strong association was found between down regulated XIST expression and decreased time to recurrence in patients treated with Taxol." (PMID 25286960, 2014). "Furthermore, a strong association has been found between XIST RNA levels and disease-free periods of ovarian cancer patients, who received Taxol in their therapeutic regiments." (PMID 27664137, 2017). "Moreover, Gene Ontology of biological pathway revealed that mesenchymal differentiation was down-regulated in OVCAR3-KRAB cells with XIST KD, suggesting that the loss of XIST may have promoted a more progenitor/stem-like state in ovarian cancer cells." (PMID 39546568, 2024). "The loss of XIST in ovarian cancer cells may have changed CSC subtypes." (PMID 39546568, 2024). "For instance, knocking out XIST can inhibit autophagy and carboplatin resistance in ovarian cancer cells through the FOXP1/AKT pathway." (PMID 40308577, 2025). "We used human ovarian cancer OVCAR3 cell line to generate XIST-knockdown cells and performed RNA-sequencing (RNA-seq) to determine the transcriptional changes associated with XIST deficiency." (PMID 40981384, 2025). "XIST’s role in ovarian cancer has only been explored in the context of therapeutic resistance using transient genetic tools (siRNA, cDNA transfection)." (PMID 39546568, 2024). "XIST affects the expression of KMT2C in ovarian cancer by enhancing the stability of KMT2C mRNA through the direct targeting of mi -93-5p." (PMID 39165358, 2024). "Overall, results from our in silico analysis demonstrated a significant downregulation of XIST in ovarian cancer patient samples, particularly in higher-grade tumors." (PMID 39546568, 2024). "By controlling the cellular plasticity of ovarian cancer cells, XIST plays a critical role in ovarian cancer progression." (PMID 39546568, 2024). "As the mesoderm is the ovaries' developmental origin and the primary source of mesenchymal SCs, our analysis thus validated that XIST KD increases the mesenchymal SC population in ovarian cancer cells." (PMID 39546568, 2024).